RPLP1 (ribosomal protein lateral stalk subunit P1)
Diseases named in the same sentence as RPLP1 in open-access papers (continued):
Sharing a sentence is not in itself a finding about the gene and the disease.
glioma (1 paper, 2022). A benign or malignant brain and spinal cord tumor that arises from glial cells (astrocytes, oligodendrocytes, ependymal cells). "Downregulated genes in glioma neurospheres, RPL and RPS families (RPLP1, RPSA and others), are indexed in the GO term “translation” (GO:0006412), as well as in the “KEGG 2021 Human Ribosome” libraries." (PMID 36231068, 2022).
gynecologic cancers (1 paper, 2018). "In 140 biopsies of gynecologic cancers (46 endometrioid and 94 ovarian), RPLP1 was up-regulated in 27% of the tumors." (PMID 30386179, 2018).
hepatocellular carcinoma (1 paper, 2023). A malignant tumor that arises from hepatocytes. "Ribosomal protein LP1 (RPLP1) is a member of the Ribosomal protein L12P family, which takes an oncogene part in hepatocellular carcinoma." (PMID 37074800, 2023).
HIV-1 infection (1 paper, 2024). The type species of lentivirus and the etiologic agent of acquired immunodeficiency syndrome (AIDS). "In summary, HIV-1 infection causes the translocation of RPLP1 from cytoplasm to the nucleus, where occupation of C/EBPβ binding sites by RPLP1 impedes the interaction of transcription factor C/EBPβ with LTR, thereby inhibiting the HIV-1 transcription." (PMID 38906865, 2024). "The translocation of RPLP1 from cytoplasm to the nucleus, induced by HIV-1 infection, represents a crucial prerequisite for its anti-HIV-1 activity." (PMID 38906865, 2024). "Overexpression of RPLP1 in Jurkat and THP1 cells reduced the susceptibility of the cells to HIV-1 infection by ~40% and ~60%, respectively, while silencing of RPLP1 expression enhanced it by ~2-fold." (PMID 38906865, 2024). "In order to assess the relationship between RPLP1 and the disease progression after HIV-1 infection, we further detected the mRNA level of RPLP1 in CD4+ T cells isolated from study participants living with HIV-1." (PMID 38906865, 2024). "Thus, RPLP1 translocation into the nucleus upon HIV-1 infection is essential for its inhibitory effect." (PMID 38906865, 2024). "Similarly, stable over-expression of RPLP1 in MT-4 cells showed lower susceptibility to HIV-1 infection and lower mRNA levels of viral rev, vpu, vif, and gag genes, while knock-down of RPLP1 expression by ~50% significantly enhanced susceptibility to HIV-1 infection and higher mRNA levels." (PMID 38906865, 2024). "Here, employing proteomics profiling, the authors identify RPLP1 to be highly expressed in long-term non-progressors of HIV-1 infection." (PMID 38906865, 2024).
Infertility (1 paper, 2014). "Rplp1 null mice could not be generated due to the infertility of Rplp1Het mice." (PMID 24959908, 2014).
lupus (1 paper, 2024). "Next, we hypothesized that the anti-TCP1 antibody could be a better biomarker than the anti-RPLP0, RPLP1, and RPLP2 antibodies, which were already known lupus autoantibodies." (PMID 39201300, 2024).
melanoma (1 paper, 2026). A malignant, usually aggressive tumor composed of atypical, neoplastic melanocytes. "RPLP1 upregulation in PBMCs may reflect a cancer-associated signal with relative enrichment in melanoma." (PMID 42302079, 2026). "Among the seven candidate genes, RPLP1 mRNA expression showed statistically significant upregulation in PBMCs cocultured with both melanoma cell lines, A375 (p = 0.0328) and SK-MEL-28 (p = 0.0311), at 24 hours compared with PBMC controls." (PMID 42302079, 2026). "The RPLP1 expression in PBMC blood samples also showed upregulation in melanoma patients compared to healthy controls (p = 0.0006)." (PMID 42302079, 2026).
nasal polyps (1 paper, 2018). "Our findings indicate that RPLP0 and RPLP1, either singly or in combination, are suitable for normalizing gene expression in nasal polyp and sinonasal tissues." (PMID 29371606, 2018).
viral infection (1 paper, 2022). "Then, CSFV infection was found to up-regulate expression of RPLP1 for enhancing viral infection." (PMID 35129423, 2022).
infection (16 papers, 2012 to 2025). The state of being infected such as from the introduction of a foreign agent such as serum, vaccine, antigenic substance or organism. "We infected HeLa, THP1, as well as HIV-negative study participants-derived CD4+ T cells and found that, compared with uninfected control cells, HIV-1 NL4-3 infection induced significant cytoplasm-to-nucleus translocation of RPLP1 by confocal microscopy." (PMID 38906865, 2024). "In contrast, the biological processes downregulated with infection include ribosomal biogenesis (Rpl3, Rpl37, Rps5, Rpl11, Rplp1, Rpl28, Rpl19, Rps28, Rps14)." (PMID 35789215, 2022). "Additionally, transfection of HEK293T cells with an HIV-1 NL4-3 proviral construct and increasing amounts of a Flag-RPLP1 expression vector also confirmed dose-dependent inhibition of HIV-1 by TZM-bl infection assay." (PMID 38906865, 2024). "Notably, almost all genes identified in this manner have elevated expression with MON‐DNJ across infection groups at 6 h with the exception of RPLP1 and ANP32A." (PMID 34287854, 2021). "Our results also showed that infection of CSFV increased cellular RPLP1 expression, which could be benefit to enhance CSFV propagation due to the positive role of RPLP1 in CSFV growth." (PMID 35129423, 2022). "Notably, taking the high expression of RPLP1 in LTNPs and the essential role of transcription in HIV-1 latency into account, RPLP1 might play potential role in non-progressive infection and latency of HIV-1." (PMID 38906865, 2024).
tumor (12 papers, 2014 to 2025). "To examine the relationship between RPLP1 protein expression and common parameters associated with tumor behavior, we compared RPLP1 levels with the clinicopathological features." (PMID 30386179, 2018). "For statistical analysis, TNBC patients (or tumor tissue specimens) were divided into high and low RPLP1 expression groups, depending on immunostaining score." (PMID 30386179, 2018). "In vitro, we determined the role and mechanistic pathways of RPLP1 in tumor metastasis in TNBC cell lines." (PMID 30386179, 2018). "When we examined the relationship between RPLP1 and tumor characteristics, we determined that high RPLP1 expression promotes cell invasion." (PMID 30386179, 2018). "Regarding tumor stages, SAMD12+ cells were predominantly expressed in stage II tumors, VIM in stage Ib, and both MKI67 and RPLP1 exhibited higher expression levels in stage IV, indicating their roles in advanced tumor progression." (PMID 40666516, 2025). "However, knocking down RPLP1 expression did not affect cell proliferation, indicating that RPLP1 largely affects motility mechanisms and metastasis, rather than tumor growth." (PMID 30386179, 2018).
cancer (8 papers, 2004 to 2026). A tumor composed of atypical neoplastic, often pleomorphic cells that invade other tissues. "Whether the stage of cancer from which the cell lines were established has an impact on RPLP1 function or necessity for survival and/or migration remains to be determined, but could possibly explain the differences observed in this study." (PMID 36769010, 2023). "In RPLP1-induced cancer metastasis, RPLP1 may increase cancer cell invasion, which is likely the result of its effect on the cancer cell epithelial-mesenchymal transition." (PMID 30386179, 2018). "An increasing number of studies show RPLP1 plays essential roles in cancer development." (PMID 30386179, 2018). "In addition, we showed that RPLP1 promotes the cell epithelial-mesenchymal transition and may play a direct role in influencing cancer spread." (PMID 30386179, 2018). "In our previous pre-experiment, we compared the proteome extracted from TNBC cancers with and without metastasis and found that RPLP1 was 1.6-fold more abundant in metastatic TNBC cancer versus non-metastatic cancer." (PMID 30386179, 2018). "In all cancer biopsies, RPLP1 localized to epithelial cells (100%) and not within surrounding tissue, while samples from control subjects exhibited low to absent staining for RPLP1 in endometrial glands (Ge) and stroma (St)." (PMID 36769010, 2023). "Furthermore, RPLP1 and RPL28 expression in BKZ-8 was affected by KJ-Pyr-9 application, suggesting an involvement of MYC signaling in ribosomal biosynthesis of AC-derived LCSC-like cells, as already shown for several cancer types." (PMID 33925297, 2021).
gynecologic tumors (3 papers, 2016 to 2024). "RPLP1 expression is also elevated in gynecologic tumors, including endometrial and ovarian cancers." (PMID 30386179, 2018). "Ribosomal P protein (RPLP0, RPLP1, RPLP2) expression was previously shown to correlate with invasiveness and metastasis in gynecologic tumors." (PMID 27741504, 2016).
RPLP1 also shares sentences with these, for which no sentence is quoted: legionellosis (10 papers); Autoimmunity (2); multiple myeloma (2); AIDS (1); Brain atrophy (1); breast tumors (1); co-infection (1); ependymoma (1); gastric cancer (1); Legionnaires' disease (1); microphthalmia (1); migraine (1); omphalocele (1); ovarian carcinoma (1); pneumonia (1); Polyarthritis (1).